UBC (ubiquitin C)
Description:
[Ubiquitin]: Exists either covalently attached to another protein, or free (unanchored). When covalently bound, it is conjugated to target proteins via an isopeptide bond either as a monomer (monoubiquitin), a polymer linked via different Lys residues of the ubiquitin (polyubiquitin chains) or a linear polymer linked via the initiator Met of the ubiquitin (linear polyubiquitin chains). Polyubiquitin chains, when attached to a target protein, have different functions depending on the Lys residue of the ubiquitin that is linked: Lys-6-linked may be involved in DNA repair; Lys-11-linked is involved in ERAD (endoplasmic reticulum-associated degradation) and in cell-cycle regulation; Lys-29-linked is involved in proteotoxic stress response and cell cycle; Lys-33-linked is involved in kinase modification; Lys-48-linked is involved in protein degradation via the proteasome; Lys-63-linked is involved in endocytosis, DNA-damage responses as well as in signaling processes leading to activation of the transcription factor NF-kappa-B. Linear polymer chains formed via attachment by the initiator Met lead to cell signaling. Ubiquitin is usually conjugated to Lys residues of target proteins, however, in rare cases, conjugation to Cys or Ser residues has been observed. When polyubiquitin is free (unanchored-polyubiquitin), it also has distinct roles, such as in activation of protein kinases, and in signaling. During ubiquitination, the acceptor ubiquitin is positioned in the active site via direct interaction with the E2 ubiquitin-conjugating enzymes such as UBE2R2. As a monoubiquitin, its C-terminal glycine is recognized as a C-degron by Cul2-RING (CRL2) E3 ubiquitin-protein ligase complexes.
Synonyms: HMG20
Tractability: Small molecule: a structure with a bound ligand is known; it has a high-quality binding pocket. Antibody: UniProt places it where antibodies can reach, with high confidence; its Gene Ontology location is reachable by antibodies, with high confidence. PROTAC: UniProt records ubiquitination sites on it; ubiquitination databases record sites on it.
Gene: Protein-coding gene on chromosome 12 (124,911,604 to 124,917,368, reverse strand). Ensembl gene ENSG00000150991.
Subcellular location: Cytoplasm (Ubiquitin); Nucleus; Mitochondrion outer membrane
Subcellular location (Human Protein Atlas): Cytosol; Acrosome; Equatorial segment
Pathways (Reactome):
Immune System: AMPK-induced ERAD and lysosome mediated degradation of PD-L1(CD274); Activation of IRF3, IRF7 mediated by TBK1, IKKε (IKBKE); Activation of NF-kappaB in B cells; Alpha-protein kinase 1 signaling pathway; Antigen processing: Ubiquitination & Proteasome degradation; CLEC7A (Dectin-1) signaling; DDX58/IFIH1-mediated induction of interferon-alpha/beta; Dectin-1 mediated noncanonical NF-kB signaling; Downstream TCR signaling; ER-Phagosome pathway; FCERI mediated NF-kB activation; GSK3B-mediated proteasomal degradation of PD-L1(CD274); IKK complex recruitment mediated by RIP1; IRAK1 recruits IKK complex; IRAK1 recruits IKK complex upon TLR7/8 or 9 stimulation; IRAK2 mediated activation of TAK1 complex; IRAK2 mediated activation of TAK1 complex upon TLR7/8 or 9 stimulation; ISG15 antiviral mechanism; Inactivation of CSF3 (G-CSF) signaling; Interferon alpha/beta signaling; Interleukin-1 signaling; JNK (c-Jun kinases) phosphorylation and activation mediated by activated human TAK1; MAP3K8 (TPL2)-dependent MAPK1/3 activation; NIK-->noncanonical NF-kB signaling; NOD1/2 Signaling Pathway; Negative regulation of FLT3; Negative regulators of DDX58/IFIH1 signaling; PD-L1(CD274) glycosylation and translocation to plasma membrane; Regulation of NF-kappa B signaling; Regulation of TBK1, IKKε (IKBKE)-mediated activation of IRF3, IRF7; Regulation of TBK1, IKKε-mediated activation of IRF3, IRF7 upon TLR3 ligation; Regulation of innate immune responses to cytosolic DNA; Regulation of signaling by CBL; SPOP-mediated proteasomal degradation of PD-L1(CD274); Signaling by CSF1 (M-CSF) in myeloid cells; TAK1-dependent IKK and NF-kappa-B activation; TICAM1, RIP1-mediated IKK complex recruitment; TICAM1,TRAF6-dependent induction of TAK1 complex; TICAM1-dependent activation of IRF3/IRF7; TNFR2 non-canonical NF-kB pathway
and 160 more pathways
Gene Ontology:
Molecular function: protein binding; RNA binding; protein tag activity
Biological process: modification-dependent protein catabolic process; protein ubiquitination
Cellular component: extracellular exosome; extracellular region; mitochondrial outer membrane; nucleus; vesicle; cytosol; cytosolic ribosome; endocytic vesicle membrane; endoplasmic reticulum membrane; endosome membrane; nucleoplasm; plasma membrane; cytoplasm
Genetic constraint (gnomAD): Loss-of-function variants: 8 observed, 29.47 expected, observed/expected ratio (o/e) 0.27, 90% interval 0.16 to 0.49. The synonymous counts are far from expectation, so gnomAD's model fits this gene poorly and the ratio says little. Missense variants: 320 observed, 658.13 expected, observed/expected ratio (o/e) 0.49, 90% interval 0.44 to 0.53. Synonymous variants: 361 observed, 227.24 expected, observed/expected ratio (o/e) 1.59, 90% interval 1.46 to 1.73.
Homologues: Orthologues: Drosophila melanogaster Ubi-p63E (99% identical), mouse Ubc (99% identical), pig UBC (99% identical), rat Ubc (99% identical), Caenorhabditis elegans ubq-1 (98% identical), tropical clawed frog ubc (89% identical), chimpanzee UBC (87% identical), Drosophila melanogaster Ubi-p5E (78% identical), zebrafish ubc (78% identical). Paralogues in human: UBB (33% identical), UBA52 (13% identical), RPS27A (13% identical), ZFAND4 (8% identical), ANKUB1 (7% identical), NEDD8 (7% identical), UBD (5% identical), UBL4A (5% identical), ISG15 (4% identical), UBL4B (4% identical).
Diseases named in the same sentence as UBC in open-access papers:
UBC is named in the same sentence as 105 diseases in open-access papers, as found by Europe PMC text mining. Sharing a sentence is not in itself a finding about the gene and the disease. The quoted sentences say what the papers report.
breast carcinoma (10 papers, 2012 to 2025). "UBC has been implicated in breast cancer and contributes to cancer metastasis." (PMID 25559354, 2014). "GAPDH, a commonly used reference gene, and UBC were the most stable in EV derived from liver and breast cancer cell lines." (PMID 37510317, 2023). "Our results overally indicated that GAPDH, YWHAZ, and UBC were the most stable reference genes in breast cancer cell lines, including MCF7, SKBR3 and MDA-MB231, and B2M and ACTB were the least stable ones." (PMID 34752497, 2021). "Regarding the combination of hepatic and breast cancer cell lines, the geNorm indicated UBC as the most stable reference gene, and the RefFinder ranked UBC and YWHAZ as two stable ones in both cellular and exosomal content." (PMID 34752497, 2021). "In breast cancer cell lines, exactly the same ranking order as the geNorm algorithm was reported in which UBC and B2M were the most and the least stable genes, respectively." (PMID 34752497, 2021). "The qISH of ESR1 and UbC by this assay was highly reproducible (R2 of 0.86 and 0.79 respectively) on serial sections of a control array with 71 breast cancer cases (YTMA 209) run in 2 independent experiments." (PMID 22606272, 2012). "Messenger RNA for ER (ESR1) and Ubiquitin C (UbC) were visualized using RNAscope probes and levels were quantified by quantitative in situ hybridization (qISH) on two Yale breast cancer cohorts on tissue microarrays." (PMID 22606272, 2012). "Furthermore, HIDEEP reveals that doxorubicin directly targets TOP2A, one of breast cancer-causing genes, and dexamethasone has impacts on TOP2A through HEPs such as ANXA1 → SUMO3 → TOP2A and NR0B1 → UBC → TOP2A." (PMID 29192270, 2017). "The results support our hypothesis that the UBC gene network plays an important role in breast cancer prognosis and therapy and it is a potential prognostic biomarker for multiple breast cancer subtypes." (PMID 24564578, 2013). "In addition, by further examining the BiNets that are significant in ER-negative breast cancer patient prognosis, we discovered a ubiquitin C (UBC) gene network that demonstrates strong prognosis power in nearly all types of breast cancer subtypes we used in this study." (PMID 24564578, 2013). "Most breast cancer cells (clusters 0–5) exhibited high levels of hypoxia‐related genes, including HSPA1A, MT2A, S100A11, MALAT1, and UBC." (PMID 39805002, 2025). "Additionally, a significant deregulation of the central node ubiquitin gene UBC, in the study, in response to progesterone, further underlined the downstream stress-regulating activities modulated by progesterone in breast cancer cells, potentially independent of the progesterone receptor (PR)." (PMID 37395734, 2023). "In breast cancer cell lines, GAPDH, TBP, and UBC were the most stable reference genes almost equally." (PMID 34752497, 2021). "Moreover, YWHAZ, UBC, and GAPDH showed the highest stability in breast cancer cell lines." (PMID 34752497, 2021).
lung carcinoma (10 papers, 2013 to 2024). "As an important member of the ubiquitin family, UBC has been widely reported as a target for the treatment of lung cancer." (PMID 36339610, 2022). "Whether other mechanisms are involved in the enhancement of radiosensitivity of UBB and UBC gene in lung cancer cells also warrants further investigation." (PMID 25820571, 2015). "The increased ubiquitin in lung cancer tissues is likely to be ascribed to UBC transcripts." (PMID 25820571, 2015). "Its ten hub genes were extracted and confirmed in the literature; seven of them (UBC, SRC, SP1, MYC, STAT3, RB1, and MAPK1) were verified to be associated with lung cancer, while the remaining three genes, JUN, NR3C1, and GRB2, were potentially new candidate lung adenocarcinoma-related genes." (PMID 26402252, 2015).
ovarian carcinoma (9 papers, 2012 to 2023). A malignant neoplasm originating from the surface ovarian epithelium. "The inducible expression of a UBC (Ubiquitin C)-targeting shRNA led to tumor regression and significant long-term survival benefits in orthotopic ovarian tumors, demonstrating the potential of targeting UBC in treating ovarian cancer." (PMID 38038814, 2023). "UBC expression was generally high in stromal regions of tumour with a low of 6.29 in a single ovarian cancer case." (PMID 29212158, 2017). "UBC is potential drug resistance-related gene in ovarian cancer." (PMID 32293263, 2020). "To generate an i.p. ovarian cancer model where tumour burden can be monitored and measured non-invasively, we developed an A2780-Rab25 stable cell line expressing the firefly luciferase gene under the control of the ubiquitin C promoter using a lentiviral gene delivery system." (PMID 26384969, 2015).
Obesity (7 papers, 2018 to 2026). Accumulation of substantial excess body fat. "We previously demonstrated that UBC-SKO mice had lower skeletal muscle mass which associates with significant obesity." (PMID 36454860, 2022). "Strikingly, we found that the UBC-SKO mouse develops significant obesity associated with both insulin resistance and glucose intolerance, and slightly decreased EE." (PMID 31404087, 2019). "To better understand the mechanism that causes obesity in the UBC-SKO mouse, we generated a 3rd cohort of (young) male mice and observed them through 4 weeks post-tamoxifen administration." (PMID 31404087, 2019). "To exclude the possibility that the obesity of UBC-SKO mice (SMRTloxP/loxP UBCERT2-Cre) was caused by Cre-induced organ toxicity we set up a separate control mouse cohort comparing UBCERT2-Cre and Cre-negative littermates on a C57/BL6 background, which is more prone to obesity." (PMID 31404087, 2019). "However, to prove whether the development of insulin resistance and fatty liver in female UBC-SKO mice might be caused by obesity, the further analysis of an older female cohort will be needed." (PMID 31404087, 2019). "Using the pathway explorative analysis tool of ingenuity pathway analysis (IPA) software, we identified two genes, TNFA and UBC (Ubiquitin C), that maximize the connection between obesity-related genes and IFNγ." (PMID 33379198, 2020). "UBC was the least stable gene in expression in all six types of tissues during the development of obesity, followed by GAPDH, ACTB, and 18S, which have been commonly used in the adipose tissue and hepatic tissue." (PMID 33330591, 2020). "Taken together, these data further support the conclusion that female UBC-SKO mice are also prone to obesity." (PMID 31404087, 2019). "As SCN disruption leads to metabolic dysfunction and obesity, loss of miR-7 in this hypothalamic region may account for the stronger obesity phenotype of UBC-cre/ERT2;miR-7fl/fl mice compared to Sim1-cre;miR-7fl/fl mice." (PMID 36175420, 2022). "Thus, we can conclude that insulin resistance and alterations in lipogenic and gluconeogenic gene expression seen in the 1st and 2nd cohorts of male mice examined 12 weeks after tamoxifen injection occur secondary to obesity in the UBC-SKO mice." (PMID 31404087, 2019). "In addition to the obesity seen, UBC-SKO mice also demonstrated profound hepatic steatosis." (PMID 31404087, 2019). "Both male and female UBC-cre/ERT2; mir-7fl/fl mice exhibited obesity on chow diet and high-fat diet (HFD), demonstrating that the miR-7 family plays an important role in the regulation of body weight." (PMID 36175420, 2022). "UBC-cre/ERT2; mir-7fl/fl mice displayed a more pronounced obesity phenotype than Sim1-cre;mir-7fl/fl mice, suggesting that miR-7 in other unidentified cell population(s) or an additive effect of miR-7 in multiple hypothalamic cell types may be implicated in weight regulation." (PMID 36175420, 2022).
melanoma (6 papers, 2015 to 2024). A malignant, usually aggressive tumor composed of atypical, neoplastic melanocytes. "Thus, mutations of ubiquitin C (UBC) may be associated with resistance to anti-PD-1 therapy in melanoma." (PMID 35013211, 2022). "We further verified that acutely induced deletion of H2-Aa in H2-Aaflox/flox;UBC-cre-ERT2 mice treated with tamoxifen significantly suppressed the growth of preestablished melanoma, as would be found in human patients." (PMID 39470607, 2024). "To specifically target the stroma, we next generated a syngeneic melanoma model by injecting murine BrafV600E-5555 cells in UBC-Cre-ERT2 mice crossed with tdTomato mice." (PMID 37516803, 2023). "Meanwhile, we identified miR-93-5p as a pro-invasion miRNA by regulating the expression of UBC in melanoma for the first time." (PMID 33897771, 2021). "Our research found that miR-18a-5p, miR-155-5p, and miR-93-5p play a key role in the mechanism of melanoma metastasis, and proved that miR-93-5p/UBC is a potential effective target for melanoma." (PMID 33897771, 2021). "Network analysis highlights UBC, a polyubiquitin precursor, as a hub gene in the module, which suggests that the majority of melanoma protein-coding genes are involved in ubiquitination pathway via interacting with UBC." (PMID 26424083, 2015). "The other three key genes, UBC, PTEN, and CCND1, were also well studied in melanoma." (PMID 33897771, 2021).
COVID-19 (5 papers, 2021 to 2024). A disease caused by infection with severe acute respiratory syndrome coronavirus 2. "Among the top genes identified by enrichment analysis as playing a key role in signalling pathways associated with coagulation-related interaction networks in COVID-19, we identified CALM1 and enhancement of its connection with PTEN and UBC." (PMID 35938548, 2022). "Similarly, other genes involved in type I interferon signaling (IFITM1 and IFITM3) and cellular activation (UBC, FOS, and DUSP1) were increased in a severity-dependent manner, suggesting an enhanced EF B-cell activity associated with an overt inflammatory condition in severe COVID-19." (PMID 35899045, 2022). "In CD14+ monocytes, HIF-1 signaling may regulate LDHA, ALDOA, TIMP1, ELOB and IFNGR2, and PPAR signaling may regulate UBC, RXRA, DBI and ACSL1 in COVID-19 patients." (PMID 33936072, 2021).
prostate carcinoma (5 papers, 2018 to 2025). A carcinoma that arises from epithelial cells of the prostate gland. "Additional studies are needed to clarify whether the protein network for methylated genes impacts prostate cancer and if this difference is associated with ubiquitin C." (PMID 29692867, 2018). "First, IHC was used to detect ubiquitin-protein (UBC) expression in prostate cancer tissues and paracancerous tissues." (PMID 34966246, 2021). "Immunofluorescence (IF) was performed to detect the colocalization of SEPT6 and UBC in prostate cancer cells." (PMID 34966246, 2021). "At the same time, overexpression of UBC could promote cell survival and proliferation, indicating that UBC affects the function of prostate cancer cells." (PMID 34966246, 2021). "In our study, we found that UBC expression was upregulated in prostate cancer tissues and cells." (PMID 34966246, 2021). "Overexpression and knockdown of UBC were performed in prostate cancer DU145 cells." (PMID 34966246, 2021). "In general, SEPT6 inhibited UBC expression, thereby reducing the overall ubiquitination level, affecting the expression level of downstream cell proliferation-related genes, and then affecting the progression of prostate cancer." (PMID 34966246, 2021). "Therefore, we selected DU145 cells as the research object for subsequent experiments to explore the role of UBC in prostate cancer." (PMID 34966246, 2021). "We aimed to study the mechanism of SEPT6 and UBC action in prostate cancer to identify new targets." (PMID 34966246, 2021). "In conclusion, SEPT6 inhibited UBC expression, thereby reducing the overall ubiquitination level, affecting the expression level of downstream cell proliferation-related genes, and thus affecting the malignancy of prostate cancer." (PMID 34966246, 2021). "The results revealed that UBC was highly expressed in prostate cancer tissues." (PMID 34966246, 2021). "UBC expression was elevated in prostate cancer tissues compared with paracancerous tissues." (PMID 34966246, 2021). "This indicates that SEPT6, as an upstream gene of UBC, could regulate the behavior of prostate cancer cells through UBC and affect cell proliferation." (PMID 34966246, 2021). "SEPT6 may target the UBC gene to affect prostate cancer, but its effect on prostate cancer cells remains unknown." (PMID 34966246, 2021). "SEPT6 as an upstream gene of UBC regulated prostate cancer cell behavior through UBC." (PMID 34966246, 2021). "IF revealed the colocalization of SEPT6 and UBC in prostate cancer cells." (PMID 34966246, 2021). "It shows that the SEPT6/UBC pathway could regulate the proliferation of prostate cancer cells, thereby affecting the progress of prostate cancer." (PMID 34966246, 2021). "The tumor formation experiment was performed to explore SEPT6/UBC effect on prostate cancer." (PMID 34966246, 2021). "This confirmed our hypothesis that oe-UBC promotes the proliferation of prostate cancer cells." (PMID 34966246, 2021). "To explore the relationship between SEPT6 and UBC on prostate cancer cells, we constructed an oe-SEPT6+oe-UBC coexpression cells." (PMID 34966246, 2021). "oe-SEPT6+oe-UBC coexpressing cells were constructed to detect the upstream and downstream relationship between SEPT6 and UBC on prostate cancer cells." (PMID 34966246, 2021). "Lastly, unique hub-genes of naive CD4+ T-cells, such as HSPA8, are reported to be expressed in CD8+ T-cells in prostate cancer, while UBC, UBB, CTNNB1, and H3-3B are not reported, rendering them novel markers for naive CD4+ T-cells." (PMID 40906153, 2025).